UGT2B17 (UDP glucuronosyltransferase family 2 member B17)
Description:
UDP-glucuronosyltransferase (UGT) that catalyzes phase II biotransformation reactions in which lipophilic substrates are conjugated with glucuronic acid to increase the metabolite's water solubility, thereby facilitating excretion into either the urine or bile. Catalyzes the glucuronidation of endogenous steroid hormones such as androgens (epitestosterone, androsterone) and estrogens (estradiol, epiestradiol).
Synonyms: BMND12; UDPGT2B17
Tractability: Small molecule: a structure with a bound ligand is known; a high-quality ligand is known. Antibody: UniProt predicts a signal peptide or a membrane-spanning region. PROTAC: its protein half-life has been measured.
Target class: Enzyme; Transferase
Gene: Protein-coding gene on chromosome 4 (68,537,146 to 68,576,413, reverse strand). Ensembl gene ENSG00000197888.
Subcellular location: Endoplasmic reticulum membrane
Pathways (Reactome):
Drug ADME: Aspirin ADME; Prednisone ADME
Metabolism: Glucuronidation
Gene Ontology:
Molecular function: glucuronosyltransferase activity; retinoic acid binding; UDP-glycosyltransferase activity
Biological process: estrogen metabolic process; steroid metabolic process; xenobiotic metabolic process
Cellular component: endoplasmic reticulum membrane; membrane
Genetic constraint (gnomAD): Loss-of-function variants: 13 observed, 19.75 expected, observed/expected ratio (o/e) 0.66, 90% interval 0.43 to 1.05. The upper end of that interval is the gene's LOEUF score, 1.05, which puts it in group 4 of 6, group 1 being the genes least tolerant of losing a copy. Missense variants: 283 observed, 374.84 expected, observed/expected ratio (o/e) 0.75, 90% interval 0.68 to 0.83. Synonymous variants: 104 observed, 135.86 expected, observed/expected ratio (o/e) 0.77, 90% interval 0.65 to 0.9.
Homologues: Orthologues: zebrafish ugt2a7 (53% identical), zebrafish ugt2b1 (53% identical), zebrafish ugt2b5 (53% identical), zebrafish ugt5a1 (42% identical), zebrafish ugt5a2 (42% identical), zebrafish si:ch73-334d15.1 (41% identical), zebrafish ugt5c1 (39% identical), zebrafish ugt5b4 (39% identical), zebrafish ugt5g1 (39% identical), zebrafish ugt5f1 (39% identical), zebrafish ugt5c3 (39% identical), zebrafish ugt5g2 (38% identical), and 93 more. Paralogues in human: UGT2B15 (94% identical), UGT2B4 (78% identical), UGT2B10 (77% identical), UGT2B7 (77% identical), UGT2B11 (77% identical), UGT2B28 (75% identical), UGT2A2 (63% identical), UGT2A3 (62% identical), UGT2A1 (53% identical), UGT1A3 (44% identical), UGT1A7 (44% identical), UGT1A8 (44% identical), and 9 more.
Diseases named in the same sentence as UGT2B17 in open-access papers:
UGT2B17 is named in the same sentence as 41 diseases in open-access papers, as found by Europe PMC text mining. Sharing a sentence is not in itself a finding about the gene and the disease. The quoted sentences say what the papers report.
prostate carcinoma (24 papers, 2013 to 2026). A carcinoma that arises from epithelial cells of the prostate gland. "Existing literature supports a causal role, particularly for UGT2B17, in regulating androgen levels and influencing hormone-sensitive diseases such as prostate cancer progression." (PMID 40264209, 2025). "In prostate cancer, UGT2B17 can interact with the kinase c-Src, which is associated with the ability of c-Src to activate the receptors of various steroid hormones." (PMID 36741721, 2022). "Of interest, genetic variants of the UGT2B15 and UGT2B17 genes were associated differently with prostate cancer risk." (PMID 35626664, 2022). "In prostate cancer, high UGT2B17 expression is associated with an increased Gleason score and risk of metastasis, CRPC progression and recurrence after prostatectomy." (PMID 36428799, 2022). "Overall, there was a significant association between UGT2B17 polymorphism and increased risk of prostate cancer (OR = 1.74, 95% CI 1.14–2.64, P < 0.001)." (PMID 24106614, 2013). "To date, a number of molecular epidemiological studies have been conducted to evaluate the effect of the UGT2B17 deletion on risk of prostate cancer." (PMID 24106614, 2013). "UGT2B17 polymorphism was significantly associated with prostate cancer risk in overall analysis (I2 = 87.4%)." (PMID 24106614, 2013). "Overall, there was a significant association between UGT2B17 status and increased risk of prostate cancer." (PMID 24106614, 2013). "Our results indicated that significant prostate cancer risks of people with UGT2B17 polymorphism are in Caucasians with OR = 1.83 (1.08–3.12) and P = 0.026." (PMID 24106614, 2013). "Considering the potential important role of UGT2B17 in prostate cancer, a meta-analyses of published studies was conducted to assess the association between UGT2B17 polymorphism and cancer risk." (PMID 24106614, 2013). "In addition, there are controversial reports regarding the association of UGT2B17 polymorphism with lung cancer, osteoporosis, and prostate cancer." (PMID 27092269, 2016). "This study has shown that the UGT2B17 polymorphism may be involved in the development of prostate cancer." (PMID 24106614, 2013). "Furthermore, the results of this meta-analysis showed that UGT2B17 polymorphism has strikingly increased the risk of prostate cancer risk susceptibility when stratified by control source." (PMID 24106614, 2013). "For example, the higher androgen abundance observed in UGT2B17 KO individuals highlights the critical role of this pathway in regulating androgen bioavailability and androgen receptor signaling, especially in men, supported by its association with the progression of prostate cancer." (PMID 40264209, 2025). "Collectively, these findings reveal a mechanism by which prostate tumors exploit UGT2B17 to evade therapy and highlight its potential as a therapeutic target in advanced prostate cancer." (PMID 41343245, 2026). "DNA methyltransferase inhibitor RG108 treatment decreases UGT2B17 expression in prostate cancer, indicating positively related expression and methylation." (PMID 40111834, 2025). "A compensatory increase in androgen sulfate conjugates was also observed, as recently reported for UGT2B17 KO male patients with prostate cancer." (PMID 40264209, 2025). "UGT2B17 and UGT2B28 germline deletions and differential expression have been associated with a number of clinical conditions such as risk and progression of prostate cancer (PCa), but also leukaemia, oesophageal, colorectal, lung, bladder and breast cancers." (PMID 36347965, 2023). "Complete deletions and differential expression of the human glycosyltransferase UGT2B17 and UGT2B28 genes are linked to prostate cancer (PCa) risk and progression, leukaemia, autoimmune and other diseases." (PMID 36347965, 2023). "In support, several bile acids including deoxycholic, hyodeoxycholic and isoursodeoxycholic acids, were efficiently conjugated in LAPC4 prostate cancer cells overexpression UGT2B17." (PMID 36347965, 2023).
prostate carcinoma (continued). "Several groups have reported the importance of miR-376c in downregulating UGT2B15 and UGT2B17 in prostate cancer." (PMID 36741721, 2022). "In prostate cancer cells, androgens can inhibit UGT2B17 expression by activating the androgen receptor, and glucuronidation leads to increased androgen secretion in the body, which will promote prostate cancer progression, forming a vicious cycle." (PMID 36741721, 2022). "Elevated UGT2B17 expression levels enhances the progression of castration-resistant prostate cancer by promoting independent androgen receptor signaling and cancer cell mitosis." (PMID 33619235, 2021). "Within the UGT2 genes, UGT2B15 and UGT2B17 have been broadly investigated in prostate cancer because of their ability to inactive DHT and testosterone." (PMID 33391440, 2021). "Perturbation of the major UGT2B17-dependent androgen catabolism pathway has the potential to affect prostate cancer (PCa) progression." (PMID 32047296, 2020). "Previous studies have shown that low expression levels of UGT2B17/15 in the LNCaP prostate cancer cell line resulted in lower intracellular glucuronide levels." (PMID 28673330, 2017). "UGT2B17 expression has been found to be significantly expressed in prostate cancer metastases and CRPC tumors, while UGT2B15 is negatively regulated in those tissues." (PMID 28673330, 2017). "Several studies have investigated the expression level of UGT2B15 and UGT2B17 in hormone naïve and castration resistant prostate cancer." (PMID 26646591, 2016). "In prostate cancer studies have focused the UGT2B15(D85Y) and the UGT2B17 gene deletion variants, although a correlation between variations in the gene copy number and serum steroids was also reported." (PMID 24027559, 2013). "One recent study has examined the localization of UGT2B15 and UGT2B17 in prostate cancer showing that UGT2B17 increased, and UGT2B15 decreased in cancer progression from benign disease to lymph node metastasis." (PMID 24027559, 2013). "A SNP cis-acting on UGT2B17 and UGT2B15 expression (rs17147338) was also associated with increased risk of prostate cancer (OR = 1.65, 95% CI = 1.00-2.70); while a stronger association among men with high Gleason sum was observed for SNPs rs4148269 and rs3100." (PMID 24267955, 2013). "On the other hand, UGT2B17 and UGT2B15 alleles that are associated with an increased risk of prostate cancer are more common in Asian populations than in Caucasian populations." (PMID 24106614, 2013). "In this present work, we examined associations between functional SNPs of UGT2B17, UGT2B15 and three other related UGT2B SNPs, and prostate cancer risk among African American and Caucasian men." (PMID 24267955, 2013). "Thus, UGT2B15 and UGT2B17 expression is negatively regulated by the binding of miR-376c to the 3′-untranslated regions of both genes in prostate cancer cells." (PMID 35626664, 2022). "A couple of studies have suggested that expression levels of the UGT2B17, B15, and 28 enzymes may be prognostic for clinicopathologic characteristics of prostate cancer." (PMID 28673330, 2017). "Neither UGT2B15 nor UGT2B17 were associated with prostate cancer specific or all-cause mortality (respectively)." (PMID 26646591, 2016). "As a result, germline CNV of UGT2B17 may have an impact on sex hormone metabolism, and thus affects the clinical course of prostate cancer." (PMID 26295840, 2015). "For instance, individuals carrying the UGT2B17 deletion have been described to show both significantly reduced overall glucuronidation rates of nicotine and its major metabolites in smokers and of androgen substrates in prostate cancer patients." (PMID 26176234, 2015).
prostate carcinoma (continued). "Furthermore, low expression of UGT2B17 further promotes the development of prostate cancer." (PMID 36741721, 2022). "Thus the expression levels of UGT2B17, B15, and B28 may be predictors of intraprostatic levels of androgens and prostate cancer phenotype." (PMID 28673330, 2017). "Elevated circulating testosterone has been associated with UGT2B28 nuclear staining which may decrease expression of UGT2B15 and UGT2B17 since studies show that their expression is elevated in patients and prostate cancer cell cultures treated with antiandrogens." (PMID 28673330, 2017). "In men, UGT2B15(D85Y) and the UGT2B17 deletion were both associated with alterations in serum steroid levels and fat mass and the UGT215(D85Y) variation has been reported to be associated with increased prostate cancer risk in unselected, Caucasian and Japanese subjects." (PMID 24027559, 2013). "Of interest, the methylation status of prostate cancer cells has a major impact on UGT2B15 and UGT2B17 gene expression." (PMID 35626664, 2022). "UGT2B17’s non-enzymatic function facilitates prostate cancer cells to resist therapy-induced stress and promote tumor progression." (PMID 41343245, 2026). "In prostate cancer and leukemic cells, alternative transcripts rather than the canonical transcript drive UGT2B17 enzyme expression." (PMID 38566115, 2024). "No study has yet, however, investigated how UGT2B15- or UGT2B17 expression in hormone naïve prostate cancer relates to time to development of CRPC." (PMID 26646591, 2016). "However UGT2B17 and B15 expression in the ADT untreated samples was not evaluated for association with clinical and pathological characteristics of prostate cancer such as BCR, PSA, pathological Gleason score, positive surgical margins, extracapsular extension and seminal vesicle invasion." (PMID 28673330, 2017). "Obviously, the genetic variation in UGT2B17 (and UGT2B15) does not explain the ethnic differences observed in prostate cancer that was discussed previously." (PMID 24106614, 2013).
breast carcinoma (10 papers, 2015 to 2022). "Indeed, this patient harbored several CNVs reported as associated with breast cancer risk involving UGT2B17, OR4C11, OR4P4, OR4S2 and GSTT1 genes." (PMID 33503040, 2021). "The UDP-glucuronosyltransferases UGT2B4 and UGT2B17 have been linked to breast cancer risk." (PMID 29743122, 2018). "In addition, after treating breast cancer with exemestane, the polymorphism of the UGT2B17 gene leads to individual differences in the drug and the upregulation of UGT2B17 expression in some patients may be related to the development of drug resistance." (PMID 36741721, 2022). "UGT2B17 is involved in the glucuronidation of exemestane, an aromatase inhibitor against breast cancer, and its copy number variation leads to individual differences in drug metabolism." (PMID 36741721, 2022). "The expression and regulation of UGT2B15 and UGT2B17 by steroid hormones were recently measured in breast cancer specimens and cell lines." (PMID 35626664, 2022). "Similar mechanisms whereby UGT2B15 and UGT2B17 influence survival through modulating the androgen signalling pathway have been reported in androgen-sensitive prostate and breast cancer." (PMID 33202946, 2020). "Moreover, other common CNVs were found to be associated with breast cancer risk through whole genome CNV genotyping studies including those disrupting OR4C11, OR4P4, OR4S2 and UGT2B17 genes." (PMID 33503040, 2021). "In addition, we have shown that UGT2B15 and UGT2B17 are prognostic in specific molecular subtypes of breast cancer as defined by the METABRIC (Molecular Taxonomy of Breast Cancer International Consortium) project." (PMID 34503303, 2021). "Altogether these data indicate that the expression of the drug metabolizing enzymes CYP2C8, UGT2B4 and UGT2B17, and transporter ABCB4 was positively regulated by SPIN1 in breast cancer." (PMID 29743122, 2018). "SPIN1 is identified as a novel target of the miR-148/152 family and enhances Adriamycin resistance by regulating drug metabolizing enzymes and transporter CYP2C8, UGT2B4, UGT2B17 and ABCB4 in breast cancer." (PMID 29743122, 2018). "Data from PPISURV and GOBO revealed that breast cancer patients with high expression of ABCB4 (P = 0.0242), CYP2C8 (P = 0.02028), UGT2B4 (P = 0.0181) or UGT2B17 (P = 0.00815) showed poorer survival than those with low expression." (PMID 29743122, 2018). "We find that SPIN1 increases breast cancer Adriamycin resistance via enhancing the expression of drug metabolizing enzymes and transporter CYP2C8, UGT2B4, UGT2B17 and ABCB4." (PMID 29743122, 2018). "We have replicated CNVs (n = 5) from the familial breast cancer study, including CNVs in genes ANKS1B19, OR4C11, OR4P4, UGT2B17, OR4C6, OR4S215." (PMID 29116104, 2017). "This is the case for UGT2B7 induced by several anti-cancer agents in liver cell models, for UGT2B15 induced by tamoxifen and UGT2B17 induced by exemestane in breast cancer-cell models, as well as for UGT1A4 induced by fulvestrant in breast cancer and liver cell models." (PMID 32047295, 2020).
osteoporosis (7 papers, 2013 to 2025). A condition of reduced bone mass, with decreased cortical thickness and a decrease in the number and size of the trabeculae of cancellous bone (but normal chemical composition), resulting in increased fracture incidence. "We further broadened our study to include associations with obesity, heart failure, osteoporosis and arthritis, in keeping with previous small size studies linking UGT2B17 SNPs to body weight and as a susceptibility gene for osteoporosis." (PMID 40264209, 2025). "A 150 kb deletion on chromosome 4q13.2 spanning the whole UGT2B17 gene has been associated with osteoporosis." (PMID 33407088, 2021). "UGT2B17 copy number variation has been associated with changes in bone mineral density and risk of osteoporosis." (PMID 29048532, 2017). "The association of the UGT2B17 CNV with AS is particularly interesting given the recent association of this CNV with osteoporosis and the proposed function as it encodes a key enzyme that inhibits androgens." (PMID 23927372, 2013). "However, a large molecular epidemiological study is needed to clarify the incidence and prevalence of osteoporotic fracture of the hip in Thai population and establish the correlation between UGT2B17 copy number variation and osteoporosis risk." (PMID 25118596, 2014). "Importantly, copies of the UGT2B17 gene have recently been associated with osteoporosis (including hip fracture)." (PMID 23927372, 2013). "Polymorphic deletions were detected in UGT2B17 and UGT2B28 and segmental duplications were found near these genes, which were associated with osteoporosis risk related to the occurrence of NAHR caused by segmental duplications." (PMID 28403820, 2017). "The metabolic profiles of UGT2B17-deficient men and UGT2B28-deficient women were most impacted, with UGT2B17 deficiency affecting various metabolites linked to metabolic diseases, arthritis, and osteoporosis." (PMID 40264209, 2025). "Note that while UGT2B17 was accurately extracted into the primary gene list by nanotatoR, as its association with osteoporosis is reported in OMIM, it does not appear in the list of genes with pathogenic variants, as no such variant is currently reported in ClinVar." (PMID 33407088, 2021). "For the UGT2B17 and UGT2B28 enzymes, the absence of their genes is not lethal; however, an increasing number of studies have found that differences in their expression patterns and/or deletions are associated with osteoporosis, autoimmune diseases and cancers." (PMID 40264209, 2025).
chronic lymphocytic leukaemia (5 papers, 2019 to 2024). "For example, high UGT2B17 expression has recently been shown to be associated with poor prognosis in chronic lymphocytic leukaemia (CLL), partly due to enhanced local inactivation of anti-leukaemic drugs (e.g., fludarabine) within CLL cells." (PMID 34503303, 2021). "UGT2B17 is also prognostic in chronic lymphocytic leukaemia (CLL), where high expression is associated with shorter treatment-free and overall survival primarily through its intracellular inactivation of anti-leukaemic drugs such as fludarabine." (PMID 34503303, 2021). "High expression of the glycosyltransferase UGT2B17 represents an independent adverse prognostic marker in chronic lymphocytic leukemia (CLL)." (PMID 38566115, 2024). "High UGT2B17 is associated with poor prognosis in untreated chronic lymphocytic leukaemia (CLL) patients and its expression is induced in non-responders to fludarabine-containing regimens." (PMID 32418995, 2020).